CXCR4 (C-X-C motif chemokine receptor 4)
Diseases named in the same sentence as CXCR4 in open-access papers (continued):
Sharing a sentence is not in itself a finding about the gene and the disease.
Granuloma (8 papers, 2015 to 2025). A compact, organized collection of mature mononuclear phagocytes, which may be but is not necessarily accompanied by accessory features such as necrosis. "Angiogenesis has also been implicated in granuloma expansion and bacterial dissemination via a mechanism that requires hypoxia-induced vascular endothelial growth factor expression and C-X-C chemokine receptor type 4 (CXCR4) signaling." (PMID 29250076, 2017). "Together, our data illustrate a pathway through which pathogenic mycobacteria induce host miR-206 expression to suppress Cxcl12/Cxcr4 signalling and prevent protective neutrophil recruitment to granulomas." (PMID 33826679, 2021). "The C3 cleavage fragments modulate CXCR4-mediated response; TNF-α, which stimulates the production of C3, is also important in granuloma formation; and its neutralization results in the loss of granuloma structure." (PMID 32344637, 2020). "The strongest effect was observed in case of IT1t application, which also reduced granuloma size, highlighting the therapeutic potential of CXCR4 blockers to counteract mycobacterial diseases." (PMID 28332618, 2017). "Furthermore, they showed that an FDA-approved CXCR4 inhibitor, plerixafor, can inhibit the formation of granulomas in clinically relevant mouse models." (PMID 39225095, 2024). "Taken together, their results show that CXCL12-expressing fibroblasts in the granulomas may recruit CXCR4-expressing immune cells, resulting in the formation of granulomas." (PMID 39225095, 2024). "This granuloma angiogenesis defect could be recapitulated with pharmacological inhibitors of CXCR4 (AMD3100 and IT1t)." (PMID 28332618, 2017). "The authors used a mouse model of lung granuloma to show that ILCs contribute to granuloma formation and that blockade of CXCR4 reduced the formation of granulomas, providing a proof of concept that sarcoidosis may be treated by CXCR4 blockade to prevent the progression of disease in patients." (PMID 39225095, 2024). "Notably, pharmacological inhibition of Cxcr4b signalling by application of two CXCR4 antagonists, namely AMD3100 and IT1t, recapitulated the angiogenesis phenotype of cxcr4b genetic knockouts with significant reduction of abnormal vasculature associated to granulomas." (PMID 28332618, 2017). "Taken together, these results show that CXCR4 signaling is necessary for formation of noninfectious tissue granulomas." (PMID 39225100, 2024). "We returned to the QDOT granuloma model to test whether CXCR4 signaling is necessary for noninfectious granuloma formation." (PMID 39225100, 2024).
Hepatitis (8 papers, 2006 to 2025). Inflammation of the liver. "Another study found that CXCR4 was closely associated with the development of the HBV-related hepatitis." (PMID 31996147, 2020). "Consistently, in hepatitis with alcoholic liver disease, CXCR4 dependent migration of lymphocytes into the tissue is significantly increased in response to treatment with ethanol, resulting in recruitment of CD4+ and CD8+ lymphocytes into liver tissue." (PMID 34386499, 2021). "Altogether, these data indicate that CXCR4 and its ligand are essential for hepatitis and provide novel ideas for further diagnosis and treatment." (PMID 34386499, 2021). "The expression of CXCR4 is significantly enhanced in HCV and HBV-associated hepatitis tissues compared to normal liver tissues." (PMID 34386499, 2021). "Studies have demonstrated the role of CXCR4 and its ligand in the recruitment of T cells to the liver in the case of hepatitis;21 however, the role of CXCR4 in B-cell activation and/or trafficking to the liver remains unknown." (PMID 38314025, 2024). "The CXCR4 signaling pathway also plays a vital role in virus-induced hepatitis." (PMID 34386499, 2021). "From the health to hepatitis, the MIF signaling network and related ligand-receptor interactions, including MIF-(CD74 + CXCR4), MIF-(CD74 + CXCR2), and MIF-(CD74 + CD44) showed a significant effect on macrophage–naïve CD4 + T cell interaction." (PMID 36221095, 2022). "Although the pathophysiology of hepatitis has not been fully elucidated, many studies have demonstrated the role of CXCR4 and its ligand in hepatitis." (PMID 34386499, 2021). "Interestingly, oval cells, known to express CXCR4 as well, have been reported to migrate to the liver along a CXCL12 gradient, established by injured hepatocytes, inducing oval-cell-aided liver regeneration in hepatitis." (PMID 16819541, 2006).
leukopenia (8 papers, 2016 to 2026). "The degree of receptor internalization defect correlated with the severity of leukopenia observed in the patients, with the E343K mutation having the least pronounced CXCR4 internalization defect associated with the mildest leukopenia phenotype." (PMID 36089616, 2022). "In PMF, male gender, older age, and MPL mutation were independently correlated with reduced CD34+CXCR4+ cells and associated with a briefer interval to develop severe anemia, large splenomegaly, thrombocytopenia, leukopenia, elevated CD34+ blood cells, blast transformation, and death." (PMID 34771488, 2021). "Altogether, these results indicate that CXCR4 antagonism corrected the peripheral blood leukopenia in Cxcr4+/1013 mice." (PMID 39588369, 2024). "It was shown that transient inhibition of CXCR4 signaling reversed circulating leukopenia in Cxcr4+/1013 mice." (PMID 39588369, 2024). "Specifically, CXCR4 antagonism normalized peripheral blood leukopenia and restored abnormal splenic B- and T-cell counts and distribution in Cxcr4+/1013 mice." (PMID 39588369, 2024). "As a consequence, [Cxcr4+/1013] mice exhibit a peripheral leukopenia affecting blood lymphocytes and neutrophils as do patients." (PMID 27111140, 2016). "This leukopenia is transiently reversed in mice and patients upon inhibition of CXCR4 with the selective antagonist AMD3100 thus demonstrating the causal role of the gain-of-CXCR4 function." (PMID 27111140, 2016). "In conclusion, we found that, in PMF patients, the CXCR4 expression on CD34+ cells was strongly correlated with severe anemia, thrombocytopenia, leukopenia, increased concentration of blood CD34+ cells, larger spleen size, and severe BM fibrosis." (PMID 34771488, 2021). "While CXCR4 antagonism corrected peripheral blood leukopenia in Cxcr4+/1013 mice, it did not appear to affect the count of red blood cells or platelets in both Cxcr4+/1013 and WT mice." (PMID 39588369, 2024). "CXCR4 antagonism corrected circulating leukopenia and mobilized functional neutrophils without disrupting granulopoiesis in the bone marrow of Cxcr4+/1013 mice." (PMID 39588369, 2024). "We provide evidence that CXCR4 antagonism corrected peripheral blood leukopenia and mobilized functional neutrophils without affecting BM granulopoiesis in Cxcr4+/1013 mice." (PMID 39588369, 2024). "However, whether CXCR4 antagonism durably corrects leukopenia in Cxcr4+/1013 mice following chronic administration has not been investigated." (PMID 39588369, 2024).
malaria (8 papers, 2015 to 2026). Malaria is a serious and sometimes fatal disease caused by a parasite that commonly infects a certain type of mosquito which feeds on humans. "The depletion of neutrophils, treatment with AMD3100 (a CXCR4 antagonist), Pulmozyme (human recombinant DNase) or Sivelestat (inhibitor of neutrophil elastase) decreased the development of malaria-associated ALI/ARDS and significantly increased mouse survival." (PMID 27926944, 2016). "Hypothesizing that the CXCR4/CXCL12 axis would be important in this model of malaria-associated ALI/ARDS, we investigated its role." (PMID 27926944, 2016). "The mutual regulation between Ly6G+ neutrophils and IL-17, along with the involvement of CD18 and CXCR4, provides insights into the complex interactions governing immune responses in malaria." (PMID 39703777, 2024). "Their responses to blood-stage malaria in both vaccinated and unvaccinated mice occurred inversely with increasing expression of Cxcr4 and decreasing expression of Cxcl12." (PMID 35214745, 2022). "Our data indicate that lung pathologies in this model of malaria-associated ALI/ARDS are orchestrated by neutrophils and that CXCR4/CXCL12 are the receptor/chemokine responsible for their trafficking." (PMID 27926944, 2016). "In malaria, previous study indicated that CXCR4 acts as a crucial host factor facilitating the transformation of Plasmodium sporozoites into exoerythrocytic form in the liver, thereby presenting a potential target for malaria prophylaxis." (PMID 39703777, 2024).
malignant glioma (8 papers, 2009 to 2024). A grade III or grade IV glioma arising from the central nervous system. "Taken together, the results strongly suggest that h-NANOG regulates CXCR4 expression in human malignant gliomas." (PMID 34638956, 2021). "Statistics shows that CXCR4 level is elevated in malignant glioma when compared to normal cells derived from the same tumor." (PMID 33123586, 2020). "The potential of CXCR4 as a promising therapeutic target for malignant glioma treatment has been extensively investigated, and several targeting drugs have already been undergoing clinical trials." (PMID 33123586, 2020). "Another factor that draws great attention for playing a crucial role in malignant glioma biological regulation is C-X-C Chemokine Receptor 4 (CXCR4), a transmembrane G-protein-coupled receptor." (PMID 33123586, 2020). "In order to determine the effect of double-targeted knockdown of miR-21 and CXCR4 on malignant glioma tumorigenicity, we first confirmed the dysregulation of these two factors in malignant glioma tissues." (PMID 33123586, 2020). "The results suggested that miR-21 and CXCR4 might play important roles in mediating malignant glioma aggressiveness, as well as the tumorigenicity." (PMID 33123586, 2020). "Therefore, double-targeted miR-21 and CXCR4 may be potential and promising therapeutic targets for malignant glioma salvage treatment." (PMID 33123586, 2020). "To determine the effect of irradiation, a treatment for malignant glioma, on CXCR4 down regulated GL26-Cit-Sh2CXCR4 cells, we implanted GL26-Cit-NT (N=10) and CXCR4 knock-down GL26-Cit-Sh2CXCR4 cells intracranially into Rag1−/− mice (N=10)." (PMID 27863376, 2016).
Myocardial fibrosis (8 papers, 2015 to 2026). "Activation of the SDF-1 and CXCR4 axis has also been linked to enhanced fibrocyte recruitment and myocardial fibrosis in vivo." (PMID 41596210, 2026). "Conversely, another group reported that systemic O/E of miR-150 in mice by AgomiR injection reduced myocardial fibrosis and protected their hearts from acute MI through decreasing monocyte migration via targeting CXCR4." (PMID 39766357, 2024). "In conclusion, our data revealed that the CXCR4 orchestrates a pro-inflammatory phenotype in macrophages by repressing PPARγ activity, thereby aggravating inflammatory response, myocardial fibrosis, and cardiac dysfunction." (PMID 35173552, 2022). "Similar gradients are likely engaged in the heart, supported by experimental evidence linking SDF-1 and CXCR4 activation to fibrocyte recruitment and myocardial fibrosis, as well as by patient data suggesting that circulating SDF-1 can promote fibrocyte migratory behavior in atrial fibrillation." (PMID 41596210, 2026). "In this setting, we recently showed that stromal derived factor-1 (SDF-1) and its cognate receptor, CXCR4, may play a critical role in the development of diffuse myocardial fibrosis in a dexoycorticosterone acetate (DOCA) hypertensive model." (PMID 26214690, 2015).
osteoporosis (8 papers, 2012 to 2026). A condition of reduced bone mass, with decreased cortical thickness and a decrease in the number and size of the trabeculae of cancellous bone (but normal chemical composition), resulting in increased fracture incidence. "IL6, CXCR4, IGF1, and PLOD2 played crucial roles in weightlessness osteoporosis, which provided a theoretical basis for the pathogenic mechanism and treatment of weightlessness osteoporosis." (PMID 35479581, 2022). "CXCR4 can target the nanoparticles to the bone microenvironment under osteoporosis based on the CXCR4/SDF-1 axis." (PMID 35033095, 2022). "Synergizing the benefits of both stem cells and biomaterials, in this work, we fabricated a synthetic stem cell nanoparticle for osteoporosis treatment using CXCR4-expressing, membrane-coated, and secretome-loaded PLGA nanoparticles." (PMID 35033095, 2022). "In a preclinical model of osteoporosis, adenoviral-mediated overexpression of CXCR4 gene was shown to be necessary for bone marrow derived mesenchymal cells, to home in the bone marrow." (PMID 22724005, 2012). "However, our findings revealed that CXCR4 was highly expressed in weightlessness osteoporosis, which may contradict the low expression state in normal osteoporosis." (PMID 35479581, 2022). "We expected MSC-Sec/CXCR4 NPs to sense SDF-1 and migrate to the site of damage, where they release loaded paracrine molecules and can reverse osteoporosis." (PMID 35033095, 2022). "In a rat model of osteoporosis, MSC-Sec/CXCR4 NP were found to accumulate in bone, and such treatment inhibited osteoclast differentiation while promoting osteogenic proliferation." (PMID 35033095, 2022). "Among them, IL6, CXCR4, IGF1, and PLOD2 were finally included in this study for follow-up analysis, because the relationships between these genes and weightlessness osteoporosis remained unclear, which was worth further analyzing." (PMID 35479581, 2022). "Notably, two critical signaling pathways, MIF‐(CD74+CXCR4) and LGALS9‐CD45, were identified as potential key regulators driving the progression of osteoporosis." (PMID 41404455, 2025). "By taking advantage of the homing and engraftment capacity induced by the SDF-1/CXCR4 axis, we coated MSC-Sec NPs with human microvascular endothelial cell (HMEC) membranes, which have high levels of CXCR4 (MSC-Sec/CXCR4 NPs) for the treatment of osteoporosis." (PMID 35033095, 2022).
Parkinson disease (8 papers, 2012 to 2025). A progressive degenerative disorder of the central nervous system characterized by loss of dopamine producing neurons in the substantia nigra and the presence of Lewy bodies in the substantia nigra and locus coeruleus. "Monocytic genes highly expressed by AMC (Cxcr4, Csk and Rac1) are known to be involved in several disease pathways such as Parkinson’s disease, Huntington’s disease and HIV infection, phagocytosis and chemokine signaling pathways." (PMID 22697290, 2012). "There was a demonstration that GDF15 may participant in the etiology of Parkinson's disease through the activation of chemokine receptor 4 (CXCR4)." (PMID 36635686, 2023).
preeclampsia (8 papers, 2014 to 2023). Preeclampsia is a hypertensive disorder of pregnancy that is characterized by new-onset hypertension with proteinuria presenting after 20 weeks of gestation, and depending on mild or severe forms may initially present with severe headache, visual disturbances, and hyperreflexia. "Low expression levels of CXCL12 and CXCR4 in peripheral blood and decidual/placental tissues are associated with miscarriage and preeclampsia in women." (PMID 37815869, 2023). "Further studies will be needed to explore the therapeutic potential of interventions aimed at the CXCL12/CXCR4 axis in pregnancy disorders related to immunological and angiogenic imbalances during early gestation, such as recurrent pregnancy loss and preeclampsia." (PMID 37815869, 2023). "On the other hand, NF-kB signaling, IL-12 signaling, Fcγ receptor-mediated phagocytosis and CXCR4 signaling which contribute to inflammation and eNOS signaling which is associated with oxidative stress may be involved in the second stage of term preeclampsia." (PMID 25392996, 2014). "The mRNA and protein expression levels of CXCR4 in trophoblast cells from patients with severe preeclampsia were lower than those in normal patients, and CXCR4 was associated with trophoblast apoptosis." (PMID 37550619, 2023). "CXCR4 is a chemokine receptor shown to be expressed in both early and term placenta and shown to have higher expression in mothers with preeclampsia and gestational hypertension." (PMID 36550527, 2022). "Low expression of SDF-1α/CXCR4 in placentas of women with preeclampsia appears to confirm the role of CXCL12/CXCR4 in this type of complication in pregnancy." (PMID 27556030, 2016). "Moreover, polymorphisms in CXCR4 and CXCL12 have been associated with preeclampsia in humans." (PMID 37815869, 2023). "Indeed, accumulating evidence in humans suggests that dysfunction of the CXCL12/CXCR4 axis may be related to pregnancy complications, including miscarriage and preeclampsia." (PMID 37815869, 2023). "Dysregulation of CXCL12/CXCR4/CXCR7 axis leads to placental dysfunction by attenuating trophoblast invasion and migration, and contributes to pregnancy disorders including preeclampsia, miscarriage, and fetal growth restriction." (PMID 33795831, 2021). "Finally, two genes differentially expressed in PTB clinical subtypes and classified as fast evolving in each of the three categories, NFIB (preeclampsia and LED) and CXCR4 (sPTB)." (PMID 26641094, 2015).
schizophrenia (8 papers, 2015 to 2023). A major psychotic disorder characterized by abnormalities in the perception or expression of reality. "Similarly, CXCR4 is a highly expressed gene in the central nervous system (CNS) and vital for normal brain morphogenesis during the embryonic stages, and is thought to be a mediator of the pathophysiology of 22q11 deletion syndrome (22q11DS), a chromosome disorder associated with schizophrenia." (PMID 33276438, 2020). "Previous studies also suggest a possible involvement of Cxcl12/Cxcr4 signaling in the neurodevelopmental disorders of GD17 MAM-treated animal model of schizophrenia." (PMID 25805966, 2015). "Cxcl12/Cxcr4 signaling might play pivotal roles in the pathogenesis of schizophrenia." (PMID 25805966, 2015).
angina (7 papers, 2012 to 2018). "Levels of the CD45dimCD133+KDR+CXCR4+ EPCs subpopulation were also significantly reduced, at baseline, in patients who underwent unstable angina or MACE during the 2-year follow-up period." (PMID 24934236, 2014). "The expressed mRNA levels of CCR1 and CXCR4 were higher in PBMCs from UA patients, comparing both stable angina ones and control subjects." (PMID 23762142, 2013). "Remarkably, patients with angina showed a significant reduction in CXCR4 surface expression on PBMCs, despite increased levels of CXCR4 RNA transcripts, but its connection to disease remains unclear." (PMID 24966838, 2014). "In a previous clinical study, increased expression of specific cardiac markers (Nkx2-5, gata-4, and mef2c) in PBMNCs, and increased number of CD34+/CXCR4+ and CD34+/CD117+ stem cells in PB were observed in ST-elevated MI patients compared to patients with stable angina and healthy Controls." (PMID 30485279, 2018). "We evaluated the mobilization of CD34+CXCR4+ cells in acute MI in comparison to patients with stable angina and control group without CAD." (PMID 22547906, 2012).